STXBP2 (syntaxin binding protein 2)
Description:
Functions in intracellular vesicle trafficking through interaction with SNAREs (soluble N-ethylmaleimide-sensitive factor-attachment protein receptors) which are essential proteins for membrane fusion. By promoting the assembly of functional STX11/SNAP23/VAMP8 SNARE complexes at the plasma membrane, regulates cytotoxic granule exocytosis in natural killer (NK) cells.
Synonyms: Munc18-2; Unc18-2; Unc-18B; UNC18B; Hunc18b; pp10122
Tractability: Antibody: its Gene Ontology location is reachable by antibodies, with high confidence. PROTAC: ubiquitination databases record sites on it; its protein half-life has been measured.
Gene: Protein-coding gene on chromosome 19 (7,636,772 to 7,647,873, forward strand). Ensembl gene ENSG00000076944.
Subcellular location: Cell membrane; Cytolytic granule membrane
Subcellular location (Human Protein Atlas): Cytosol
Pathways (Reactome):
Hemostasis: Platelet degranulation
Immune System: Other interleukin signaling
Gene Ontology:
Molecular function: protein binding; protein-macromolecule adaptor activity; syntaxin-3 binding; syntaxin-1 binding; SNARE binding
Biological process: cytotoxic T cell degranulation; leukocyte mediated cytotoxicity; neutrophil degranulation; SNARE complex assembly; presynaptic dense core vesicle exocytosis; regulation of mast cell degranulation; regulated exocytosis; vesicle-mediated transport
Cellular component: azurophil granule; cytolytic granule; cytolytic granule membrane; cytosol; extracellular exosome; immunological synapse; plasma membrane; specific granule; tertiary granule; extracellular region; secretory granule; apical plasma membrane; phagocytic vesicle; presynapse; zymogen granule membrane
Genetic constraint (gnomAD): Loss-of-function variants: 48 observed, 69.82 expected, observed/expected ratio (o/e) 0.69, 90% interval 0.54 to 0.87. The upper end of that interval is the gene's LOEUF score, 0.87, which puts it in group 3 of 6, group 1 being the genes least tolerant of losing a copy. Missense variants: 687 observed, 783.98 expected, observed/expected ratio (o/e) 0.88, 90% interval 0.82 to 0.93. Synonymous variants: 358 observed, 323.92 expected, observed/expected ratio (o/e) 1.11, 90% interval 1.01 to 1.21.
Gene-disease validity (ClinGen):
ClinGen rates the evidence that STXBP2 causes each of these diseases.
familial hemophagocytic lymphohistiocytosis 5 (autosomal recessive): Definitive.
Homologues: Orthologues: chimpanzee STXBP2 (96% identical), macaque STXBP2 (96% identical), rat Stxbp2 (95% identical), mouse Stxbp2 (95% identical), guinea pig STXBP2 (94% identical), dog STXBP2 (93% identical), rabbit STXBP2 (93% identical), pig STXBP2 (91% identical), zebrafish stxbp2 (68% identical), tropical clawed frog stxbp2 (67% identical), Caenorhabditis elegans uncp-18 (31% identical). Paralogues in human: STXBP3 (47% identical), SCFD1 (23% identical), VPS45 (22% identical), SCFD2 (19% identical), VPS33B (19% identical), VPS33A (18% identical).
Diseases named in the same sentence as STXBP2 in open-access papers:
STXBP2 is named in the same sentence as 62 diseases in open-access papers, as found by Europe PMC text mining. Sharing a sentence is not in itself a finding about the gene and the disease. The quoted sentences say what the papers report.
hemophagocytic lymphohistiocytosis (12 papers, 2014 to 2024). "The other two genes (LY9 and STXBP2) cause or are linked to hemophagocytic lymphohistiocytosis (HLH) disorders, including macrophage activation syndrome (MAS)." (PMID 36588876, 2022). "Interestingly, mutations in other regulators of the SNARE complex, namely STXBP2, can lead to altered NK cell degranulation, hemophagocytic lymphohistiocytosis and colitis." (PMID 31663849, 2019). "Others include known genetic causes of hemophagocytic lymphohistiocytosis (HLH) such as defects in the genes PRF1, UNC13D, STX11, STXBP2, LYST, and RAB27A." (PMID 38624552, 2020).
Familial hemophagocytic lymphohistiocytosis (7 papers, 2016 to 2024). Familial Hemophagocytic lymphohistiocytosis (FHL) is a rare primary immunodeficiency characterized by a macrophage activation syndrome (see this term) with an onset usually occurring within a few months or less common several years after birth. "Germline mutations in genes involved in perforin-granzyme-mediated cytotoxicity such as PRF1, UNC13D, STX11, and STXBP2 were known to cause familial hemophagocytic lymphohistiocytosis (FHL)." (PMID 38404589, 2024). "Mutations in STXBP2 are associated with familial hemophagocytic lymphohistiocytosis (FHL), a life-threatening hyperinflammatory syndrome that results from an uncontrolled and ineffective immune response due to dysfunction of cytotoxic T lymphocytes (CTLs) and NK cells." (PMID 28380445, 2017). "Germline mutations in genes involved in perforin-granzyme-mediated cytotoxicity such as PRF1, UNC13D, STX11, and STXBP2 were known to induce familial HLH (FHL)." (PMID 38404589, 2024). "CES resulted in a diagnosis of STXBP2-related Familial hemophagocytic lymphohistiocytosis (OMIM# 613101)." (PMID 38716412, 2024). "MVID can present in some patients diagnosed with familial hemophagocytic lymphohistiocytosis (FHL) type 5, which is a rare, inherited, hyperinflammatory syndrome caused by mutations in the STXBP2 gene." (PMID 35893420, 2022). "Bi-allelic null mutations affecting UNC13D, STXBP2, or STX11 result in defects of lymphocyte cytotoxic degranulation and commonly cause familial hemophagocytic lymphohistiocytosis (FHL) in early life." (PMID 28848550, 2017). "STXBP2, which encodes syntaxin-binding protein 2, has a role in cytotoxic T and NK cell functions and is associated with familial hemophagocytic lymphohistiocytosis (FHL), a clinical phenotype not found in this patient." (PMID 27379089, 2016). "Mutations in the HPLH1 gene are responsible for familial hemophagocytic lymphohistiocytosis type 1 (FLH-1), a mutation in the PRF1 gene causes FLH-2, mutations in the UNC13D gene cause FHL-3, mutations in the STX11 gene cause FHL-4, and a mutation in the STXBP2 (UNC18B) gene causes FHL-5." (PMID 36766791, 2023).
Griscelli syndrome type 2 (3 papers, 2015 to 2025). Griscelli syndrome type 2 (GS2) is a rare, inherited condition that affects the skin, hair, and immune system. "Patients were divided into four groups: 1) with PRF1 mutation (n = 46), 2) with UNC13D mutation (n = 38), 3) with STX11/STXBP2 mutation (n = 25) and 4) with Griscelli syndrome type 2/ Chediak–Higashi syndrome (GS2/CHS) diagnosis (n = 44)." (PMID 40263637, 2025). "In 13 out of the 24 (52%) a genetic diagnosis was achieved: PRF1 n = 4 (FHL2), STX11 n = 2 (FHL4), and STXBP2 n = 4 (FHL5), RAB27A n = 2 (Griscelli syndrome type 2), BIRC4 n = 1 (XIAP)." (PMID 30697212, 2018).
macrophage activation syndrome (3 papers, 2022 to 2025). A complication of rheumatic disease that is caused by excessive activation and uncontrolled proliferation of T lymphocytes and well-differentiated macrophages. "Another gene, STXBP2, has also been implicated in SLE-related macrophage activation syndrome." (PMID 40599891, 2025).
Sepsis (3 papers, 2024 to 2025). Sepsis is defined as life-threatening organ dysfunction caused by a dysregulated host response to infection. "HLH is a hyperinflammatory syndrome in which familial (primary) forms arise from biallelic variants in cytotoxic-pathway genes (e.g., PRF1, UNC13D, STX11, STXBP2), and in neonates the presentation may closely mimic sepsis." (PMID 41477640, 2025).
autoimmune disease (2 papers, 2014 to 2025). A disorder resulting from loss of function or tissue destruction of an organ or multiple organs, arising from humoral or cellular immune responses of the individual to their own tissue constituents. "While primary HLH typically manifests in children due to mutations in genes such as PRF1, UNC13D, STX11 and STXBP2, secondary HLH is more common in adults and is usually triggered by infections, cancers, autoimmune disorders or immunosuppressive therapy." (PMID 41181728, 2025).
cholestasis (2 papers, 2020 to 2021). Impairment of the bile flow caused by obstruction within the liver, or outside the liver in the bile duct system. "Cholestasis has not been reported from the very few MVID patients with STX3 or STXBP2 mutations so far." (PMID 33924896, 2021).
colitis (2 papers, 2014 to 2019). Inflammation of the colon. "In patients with mutations in STXBP2, severe chronic inflammatory bowel disease (colitis) and hypogammaglobulinemia were frequently found." (PMID 24509696, 2014).
COVID-19 (2 papers, 2022). A disease caused by infection with severe acute respiratory syndrome coronavirus 2. "As seen in the severe COVID-19 patient reported herein, the STXBP2 p.Ala429Val mutation contributed to decreased NK degranulation and cell lysis ability." (PMID 35207437, 2022). "In this report, we present an 18-year-old female with severe COVID-19 and features of HLH, who was found to have a rare (0.036%, Genome Aggregation Database) heterozygous STXBP2 (c.1286C > T, p.Ala429Val) missense mutation and defective NK cell killing." (PMID 35207437, 2022). "The STXBP2 rs2303115 G/A showed the GG genotype was more frequent in COVID-19 vs. the H1N1 groups." (PMID 36016321, 2022). "Thus, heterozygous missense mutations in perforin pathway genes important for lymphocyte cytolytic activity, including STXBP2, may contribute to disease severity of infectious disease such as COVID-19." (PMID 35207437, 2022).
Langerhans cell histiocytosis (2 papers, 2021 to 2022). Langerhans cell histiocytosis (LCH) is a systemic disease associated with the proliferation and accumulation (usually in granulomas) of Langerhans cells in various tissues. "A patient with an STXBP2 (c.568C > T, p.Arg190Cys) mutation developed sHLH in the setting of Langerhans cell histiocytosis; NK cell lysis was found to be decreased, improving with sHLH therapies and CD107a expression was significantly lower than controls." (PMID 35207437, 2022).
microvillus inclusion disease (2 papers, 2022 to 2024). Microvillus inclusion disease (MVID) is a very rare, severe, malabsorbative syndrome characterized clinically by protracted or intractable neonatal secretory diarrhea and histologically by inclusion bodies on the intestinal epithelium. "One such example is microvillus inclusion disease (MVID), a congenital enteropathy characterized by early-onset diarrhea, caused by mutations in myosin 5b (MYO5B), STX3 or syntaxin binding protein 2 (STXBP2)." (PMID 38799985, 2024).
Primary hemophagocytic lymphohistiocytosis (2 papers, 2022 to 2024). "Rare heterozygous missense variants in genes responsible for primary hemophagocytic lymphohistiocytosis (LYST, STXBP2, PRF1, UNC13D, AP3B1, and DOCK8) were found in patients with MIS-C." (PMID 38397896, 2024). "Thirty-nine children were diagnosed with MIS-C, and 25.4% of the 39 MIS-C patients harbored rare heterozygous missense mutations either in primary hemophagocytic lymphohistiocytosis (pHLH) genes (LYST, STXBP2, PRF1, UNC13D, AP3B1) or the HLH-associated gene DOCK8 (four variants)." (PMID 35336791, 2022).
Bladder Urothelial Carcinoma (1 paper, 2022). "In contrast, high expression of STXBP2 was a protective factor in BLCA (Bladder Urothelial Carcinoma), SARC (Sarcoma), SKCM, THYM (Thymoma), and CHOL (Cholangiocarcinoma)." (PMID 36119081, 2022).
endometrial cancer (1 paper, 2025). Primary or metastatic malignant neoplasm involving the endometrium (mucous membrane that lines the endometrial cavity).
Epstein-Barr virus infection (1 paper, 2019). An infection that is caused by Epstein-Barr virus. "This is the first case report in which adult HLH was associated with novel digenic mutations of STXBP2 and LYST combined with Epstein-Barr virus infection." (PMID 30782130, 2019).
erythroleukemia (1 paper, 2022). Acute erythroid leukemia characterised by the presence of at least 50% erythroid precursors and at least 20% myeloblasts in the bone marrow. "The WT and mutant STXBP2 transduced NK-92 cells were stimulated with NK-sensitive K562 erythroleukemia target cells in vitro, and NK cell degranulation and cytolysis were measured via CD107a expression and Live/Dead near-IR dye, respectively." (PMID 35207437, 2022).
Huntington disease (1 paper, 2021). Huntington disease (HD) is a rare neurodegenerative disorder of the central nervous system characterized by unwanted choreatic movements, behavioral and psychiatric disturbances and dementia. "Another gene selected was syntaxin binding protein 2 (Stxbp2) that belongs to the Syntaxin family, members of which have been suggested to influence the development of Huntington’s disease by interaction alterations in the cortico-striatal pathway." (PMID 33704701, 2021).
Jacobsen syndrome (1 paper, 2025). A multiple congenital anomaly/intellectual disability contiguous gene syndrome caused by partial deletion of the long arm of chromosome 11. "Two (8.3%) met IUIS criteria for IEIs (Jacobsen syndrome and STXBP2)." (PMID 41009569, 2025).
metabolic acidosis (1 paper, 2025). "Chronic diarrhoea is linked to familial hemophagocytic lymphohistiocytosis type 5 and metabolic acidosis in patients with syntaxin-binding protein 2 (STXBP2/MUNC18-2) mutation and to neurological impairments in patients with syntaxin 3 (STX3) mutation, respectively." (PMID 40310351, 2025).
myocardial infarction (1 paper, 2017). Gross necrosis of the myocardium, as a result of interruption of the blood supply to the area, as in coronary thrombosis. "STXBP2 may thus be a novel susceptibility locus for myocardial infarction in Japanese." (PMID 28380445, 2017).
neutropenia (1 paper, 2016). A decrease in the number of neutrophils found in the blood. "Compound heterozygous mutations in STXBP2 (p.C158Wfs*78 and p.P334L) were also identified in one patient (#15) who had very low B cells and a prior severe EBV infection associated with neutropenia that responded to corticosteroids, cyclosporine, and filgrastim." (PMID 27379089, 2016).
Polyhydramnios (1 paper, 2022). The presence of excess amniotic fluid in the uterus during pregnancy. "Together, the occurrence of polyhydramnios associated with MVID was not restricted to either the MYO5B, STX3, or STXBP2 variants." (PMID 35893420, 2022).
tumor (5 papers, 2022 to 2025). "GGA2, FER and STXBP2: Exhibit varied expression patterns, with some showing significant differences between tumour and normal tissues." (PMID 41362116, 2025). "Further multi-omics analysis revealed that cryoablation activates the lysosomal pathway in tumor tissues, leading to overexpression of key proteins such as SNAP23 (Synaptosome Associated Protein 23) and STXBP2 (Syntaxin Binding Protein 2)." (PMID 38384806, 2024). "PUF60 contributes to apoptosis and transcriptional regulation, SFXN3 is a mitochondrial serine transporter, SERPINB1 regulates the innate immune response, SERPINB5 is a tumor suppressor, and STXBP2 regulates exocytosis." (PMID 36400567, 2023). "During this period, lysosome-related pathways are activated, resulting in overexpression of SNAP23 and STXBP2, activation of immune effector cells, suppression of the release of immunosuppressive factors, and finally, enhancement of anti-tumor immunity." (PMID 36119081, 2022). "Cell destruction leads to the activation of anti-tumor immunity due to the release of tumor-related antigens such as SNAP23 and STXBP2, leading to an abscopal effect." (PMID 36612192, 2022).
cancer (3 papers, 2022 to 2025). A tumor composed of atypical neoplastic, often pleomorphic cells that invade other tissues. "Further analysis of TCGA pan-cancer data revealed that both SNAP23 and STXBP2 overexpression were associated with a better prognosis of SKCM." (PMID 36119081, 2022). "Further to investigate the relationship between SNAP23 and STXBP2 and patient survival, we further analyzed the pan-cancer data in TCGA." (PMID 36119081, 2022).
infection (2 papers, 2022 to 2025). The state of being infected such as from the introduction of a foreign agent such as serum, vaccine, antigenic substance or organism. "Notably, genes such as Cyp26b1, Dbp, Kcng1, Cdca7l, Paxip1, Stxbp2 and Gpi1 were also observed to be significantly up-regulated (p<0.05) in the hMHC mice on various days post-infection." (PMID 40822594, 2025).
STXBP2 also shares sentences with these, for which no sentence is quoted: Ataxia (2 papers); Chediak–Higashi Syndrom (2); immune disease (2); acquired immunodeficiencies (1); Autoimmunity (1); bowel dysfunction (1); cholangiocarcinoma (1); chronic granulomatous disease (1); chronic kidney disease (1); congenital enteropathy (1); coronary atherosclerosis (1); diabetes mellitus (1); epilepsy (1); familial hemophagocytic lymphohistiocytosis type 1 (1); genetic diseases (1); hematological malignancies (1); Hemophagocytosis (1); Hepatosplenomegaly (1); Hypertension (1); hypertriglyceridemia (1); hyperuricemia (1); hypogammaglobulinemia (1); Immunodeficiency (1); Infantile encephalopathy (1); infectious disease (1); inflammatory bowel disease (1); Lymphadenopathy (1); neurodevelopmental disorder (1); Obesity (1); Pancytopenia (1).
A further 7 diseases each share a sentence with STXBP2 in 1 paper.